PLK1 (polo like kinase 1)
Diseases named in the same sentence as PLK1 in open-access papers (continued):
Sharing a sentence is not in itself a finding about the gene and the disease.
breast tumors (21 papers, 2011 to 2025). "The gene signature associated with high 14-3-3ζ levels in breast tumors encompassed many with functions in mitosis and cytokinesis, including aurora kinase-B, polo-like kinase-1, CDC25B, and BIRC5/survivin." (PMID 21707964, 2011). "The article published reported that PLK1 has the ability to alter the transcriptional profile of Her2+ breast tumors in the living environment, affecting the effector capacity of NK and T cells." (PMID 40612941, 2025). "For instance, PLK1 overexpression has been shown to inhibit the development of Kras- or Her2-induced breast tumors by interfering with mitotic processes and cytokinesis." (PMID 40612941, 2025). "Our findings that the proteolytic regulator PAI1 and cell cycle kinase PLK1 drive fibroblast-induced therapy resistance are also supported by transcriptomic analyses of HER2+ breast tumors in the clinic." (PMID 39513002, 2024). "High PLK1 expression was also described in patient-derived xenografts (PDX) from bone metastasis compared to matched primary breast tumors." (PMID 37447165, 2023). "In order to determine the prognostic significance of PLK1 expression pattern in human breast tumours, we analysed PLK1 mRNA levels in a large series of 441 primary breast tumours from patients with known clinical/pathological status and long-term outcome." (PMID 32792481, 2020). "Alongside, breast tumor patients that have an elevated expression signature of these Plk1-dependent gene set, positively correlate with a favorable clinical prognosis." (PMID 30862113, 2019). "For instance, Plk1 histological expression analysis showed that breast tumors with increased levels of PLK1 protein have a better prognosis when compared to the samples with very little or an absent PLK1 presence." (PMID 30862113, 2019). "In this study we have analyzed the expression of MAP9/ASAP and its two partners AURKA and PLK1 in colorectal and breast tumors." (PMID 24876664, 2014). "In the present study, we confirm that a proportion of breast tumours are positive for PLK1 protein expression as judged by immunohistochemical staining." (PMID 22405092, 2012). "Analysis of publicly available, clinical transcriptomic datasets revealed that HER2-targeted therapy fails to suppress PLK1 expression in stroma-rich HER2+ breast tumors and that high PAI1 gene expression associates with high stroma density." (PMID 39513002, 2024). "Likewise, analysis of IHC images in the HPA database revealed that PLK1 expression was higher in the breast tumor tissues compared to the normal tissues." (PMID 38186570, 2023). "Breast tumors have a higher level of PLK1 expression compared with normal breast tissue (left violin plot) and is more highly expressed in patient TNBC compared to Luminal A tumors (p = 1.01 × 10−6), this perhaps correlates with TNBC’s aggressive characteristics (right violin plot)." (PMID 34561554, 2022). "In both cohorts, PLK1 expression was higher in the group of CCND1-amplified breast tumours." (PMID 32792481, 2020). "In summary, these data show that blocking MEK1/2/PLK1 substantially impacts tumor growth in multiple models of basal‐like, triple‐negative breast cancer and represents a novel candidate strategy for treating breast tumors that exhibit high CEP55 expression." (PMID 30108112, 2018).
breast tumors (continued). "Patients with primary breast tumors had lower expression of PLK2 mRNA, but higher levels of PLK1 mRNA, relative to normal breast tissue." (PMID 35156101, 2021). "Immunohistochemical analysis revealed a strong expression of PLK1 and Ki67 in the PDX, the patient’s bone metastasis and primary breast tumour." (PMID 32792481, 2020). "Analysis of these miR-10b* targets by immunohistochemistry (IHC) in ten matched breast tumour and peritumoural tissues (from the cohort analysed by microarray miR profiling) showed remarkable increased staining of BUB1, PLK1 and CCNA2 in the tumour tissues." (PMID 23125021, 2012). "We also identified a two-gene expression signature (PLK1 + AURKA) which discriminated between DNA aneuploid and DNA diploid breast tumor samples." (PMID 21352579, 2011).
esophageal squamous cell carcinoma (21 papers, 2009 to 2025). Esophageal squamous cell carcinoma (ESCC) is a type of esophageal carcinoma (EC) that can affect any part of the esophagus, but is usually located in the upper or middle third. "For instance, inhibitors targeting polo-like kinase 1 (PLK1) can enhance the anti-tumor activity of cisplatin by inducing pyroptosis in esophageal squamous cell carcinoma." (PMID 39949740, 2025). "For instance, targeted inhibition of PLK1 has significantly hindered esophageal squamous cell carcinoma (ESCC) progression and reduced the resistance to doxorubicin, a chemotherapeutic drug." (PMID 39353904, 2024). "In esophageal squamous cell carcinoma, downregulation of PLK1 can inhibit the pentose phosphate pathway, reduce NADPH and GSH levels, thereby promoting ferroptosis, and increasing the sensitivity of cancer cells to radiotherapy and chemotherapy." (PMID 39314848, 2024). "PLK1 is reported to enhance anoikis resistance via inhibiting β-catenin degradation in esophageal squamous cell carcinoma, and inhibition of PLK1 could trigger cell apoptosis to block LUAD progression." (PMID 38345559, 2024). "Furthermore, the use of polo-like kinase 1(PLK1) inhibitors alongside cisplatin in the treatment of esophageal squamous cell carcinoma has been shown to enhance the therapeutic response." (PMID 38304430, 2024). "On the other hand, sunitinib 26 acts as a PLK1 kinase inhibitor and induces pyroptosis in esophageal squamous cell carcinoma (ESCC)." (PMID 39316325, 2025). "Inhibition of PLK1 by BI2536 treatment in esophageal squamous cell carcinoma (ESCC) induced pyroptosis both in vitro and in vivo through the BAX/caspase-3/GSDME pathway and boosted the sensitivity to cisplatin." (PMID 35719948, 2022). "In esophageal squamous cell carcinoma (ESCC), BI2536, an inhibitor of polo-like kinase 1(PLK1), was found to activate caspase-3 and BAX in combination with cisplatin, resulting in GSDME disruption and increased DNA damage." (PMID 35359956, 2022). "In addition, in esophageal squamous cell carcinoma (ESCC), TFAP2C promotes the cell cycle, where TFAP2C activates the expression of polo-like kinase 1 (PLK1) by interacting with hematological and neurological expressed 1 like (HN1L)." (PMID 37291585, 2023). "For example, the polo-like kinase 1 (PLK1) inhibitor, BI2536, enhances the chemical sensitivity of cisplatin by inducing pyroptosis in esophageal squamous cell carcinoma, and cisplatin combined with BI2536 can induce pyroptosis in esophageal squamous cell carcinoma at low doses." (PMID 35883480, 2022).
medulloblastoma (20 papers, 2012 to 2025). A malignant, invasive embryonal neoplasm arising from the cerebellum. "In MYC−driven medulloblastoma, inhibition of PLK1 stabilizes FBXW7, underscoring its tumor‐suppressive function, while blocking ELK1−mediated transcription activates FBXW7 and suppresses MCL1, leading to cytotoxicity." (PMID 40370434, 2025). "A similar PLK1/Fbxw7/Myc axis was also identified in c-MYC-driven medulloblastoma, with PLK1 antagonizing Fbxw7-mediated c-Myc degradation." (PMID 36902175, 2023). "Here, we identify PLK1 as a potential co-target for a combination therapy with the class I HDACi entinostat in MYC-amplified medulloblastoma and investigate synergistic interactions in vitro and in vivo." (PMID 37183219, 2023). "PLK1 inhibitors have been previously employed in medulloblastoma, showing promise as radiosensitizers and in combination with BET inhibitors." (PMID 37183219, 2023). "Microarray results showed that the expression of c-MYC and PLK1 was positively correlated in medulloblastoma." (PMID 33494392, 2021). "Polo-like kinase 1 (PLK1) is highly expressed in group 3 medulloblastoma (MB), and it has been preclinically validated as a cancer therapeutic target in medulloblastoma." (PMID 33494392, 2021). "We previously demonstrated that PLK1 is highly expressed in MYC-driven medulloblastoma and that the inhibition of PLK1 with BI2536 suppresses tumor cell growth." (PMID 33494392, 2021). "Despite considerable study, it is not yet clear why the expression of PLK1 is upregulated and how a high level of PLK1 reprograms cells to promote the cancer state in medulloblastoma." (PMID 33494392, 2021). "Further, downstream targets of FOXM1 such as PLK1 and cyclin B1 were significantly reduced thus affecting the cell cycle progression in medulloblastoma cell lines." (PMID 31541075, 2019). "In a previous study, we demonstrated that reducing levels of PLK1 with RNAi significantly decreased the ability of medulloblastoma cells to form colonies." (PMID 29228610, 2017). "We previously showed that PLK1 plays a key role in regulating stem-like characteristics of medulloblastoma cells." (PMID 29228610, 2017). "In children with medulloblastoma, PLK1 was independently correlated with poor outcomes through using Cox regression analyses in two patient cohorts." (PMID 28724602, 2017). "There were 57 up-regulated genes common to the tumors induced by rb1 somatic inactivation (zebrafish tumors) and human medulloblastomas and PNETs most of which were involved in cell cycle progression and mitosis (such as cdk1, aurka, plk1, etc.)." (PMID 28903419, 2017). "We and others have identified PLK1 as a potential therapeutic target in brain tumors including glioblastoma and medulloblastoma." (PMID 27538997, 2016). "We chose to initially examine polo-like kinase 1 (PLK1) based on our previous experience with this kinase as a radio-sensitizer in another brain tumor, medulloblastoma." (PMID 27538997, 2016). "While PLK1 mRNA expression is upregulated in medulloblastoma, the significance of PLK1 in the pathogenesis and management of this pediatric brain tumor is not well understood." (PMID 22390279, 2012). "In total, our data make a strong argument for further exploring the role of PLK1 inhibition in medulloblastoma." (PMID 22390279, 2012). "Pediatric cerebellum (UPN 514 and 605) and adult cerebellum have minimal PLK1 protein expression while all the medulloblastoma cell lines have increased but varied levels of PLK1 protein." (PMID 22390279, 2012). "We next examined PLK1 protein expression in normal pediatric and adult cerebellum as well as a panel of medulloblastoma cell lines." (PMID 22390279, 2012). "Consistent with our patient tissue data, all medulloblastoma cell lines tested expressed PLK1 mRNA at significantly higher levels (p < 0.01) compared to normal pediatric and adult cerebellum." (PMID 22390279, 2012).
medulloblastoma (continued). "In this study we demonstrate that PLK1 mRNA is overexpressed in two independent medulloblastoma cohorts when compared to normal cerebellum." (PMID 22390279, 2012). "We next evaluated expression of PLK1 mRNA in a panel of well-characterized medulloblastoma cell lines." (PMID 22390279, 2012). "Analysis of protein kinase gene expression revealed that expression of multiple protein kinases was altered in medulloblastoma, including several components of the mitotic machinery such as aurora kinase A and PLK1." (PMID 22390279, 2012). "In particular our data show that PLK1 is a target in all subgroups of medulloblastomas making it ideal for clinical trials." (PMID 22390279, 2012). "Inhibition of PLK1 by RNAi significantly decreased medulloblastoma cell proliferation and clonogenic potential and increased cell apoptosis." (PMID 22390279, 2012). "Our data suggest that targeting PLK1 with small molecule inhibitors, in combination with radiation therapy, is a novel strategy in the treatment of medulloblastoma that warrants further investigation." (PMID 22390279, 2012). "Once again, inhibition of PLK1 mRNA by RNAi significantly decreased medulloblastoma cell growth as measured by their ability to form colonies." (PMID 22390279, 2012). "Analysis of our previous data suggests that polo-like kinase 1 (PLK1) is a potential therapeutic target in medulloblastoma." (PMID 22390279, 2012). "Inhibition of PLK1 impaired tumor sphere formation of medulloblastoma cells and decreased the expression of SRY (sex determining region Y)-box 2 (SOX2) mRNA in tumor spheres indicating a possible role in targeting tumor inititiating cells." (PMID 22390279, 2012). "Our data, together with previous studies, strongly suggest that targeting PLK1 with small molecule inhibitors in combination with radiation therapy is both a novel strategy in the treatment of medulloblastoma and one that warrants further study." (PMID 22390279, 2012). "Decreasing the expression of PLK1 mRNA by RNAi clearly resulted in growth suppression and induction of apoptosis in medulloblastoma cells." (PMID 22390279, 2012). "Our results demonstrated that PLK1 inhibition enhanced FBXW7 stability in medulloblastoma." (PMID 33494392, 2021). "We and others have previously identified PLK1 as a key regulator of medulloblastoma cell viability." (PMID 33494392, 2021). "To evaluate the mechanisms by which PLK1 is overexpressed in MYC-driven medulloblastoma, we first asked whether c-MYC activates PLK1 transcription in medulloblastoma." (PMID 33494392, 2021). "In this study, our goal was to evaluate PLK1 as a potential therapeutic target in medulloblastoma." (PMID 22390279, 2012). "To evaluate whether decreased expression of PLK1 mRNA resulted in apoptosis in medulloblastoma, we analyzed Annexin V expression on medulloblastoma cells by flow cytometry." (PMID 22390279, 2012). "We examined the expression of PLK1 mRNA in medulloblastoma tumor samples using microarray analysis." (PMID 22390279, 2012). "To examine whether PLK1 was functionally important for medulloblastoma tumorigenesis, we initially decreased expression of PLK1 mRNA by siRNA and shRNA." (PMID 22390279, 2012). "Furthermore, we show that inhibition of PLK1 by a small molecule inhibitor, BI 2536, results in a significant reduction in the proliferation of medulloblastoma cells both in short-term and long-term assays." (PMID 22390279, 2012). "We determined the expression of PLK1 mRNA in two independent cohorts of medulloblastoma patients and investigated the effect of PLK1 inhibition by RNA interference (RNAi) and by the small molecule drug BI 2536 on medulloblastoma cells in vitro." (PMID 22390279, 2012). "To further elucidate whether there was a correlation within the subgroups of medulloblastoma, we examined expression of PLK1 mRNA in a cohort of 120 recently described medulloblastoma samples." (PMID 22390279, 2012).
medulloblastoma (continued). "We next evaluated the hypothesis that inhibition of PLK1 mRNA impairs tumor initiating cells in medulloblastoma." (PMID 22390279, 2012). "Similarly, a low nanomolar concentration of BI 2536, a small molecule inhibitor of PLK1, potently inhibited cell growth, strongly suppressed the colony-forming ability, and increased cellular apoptosis of medulloblastoma cells." (PMID 22390279, 2012). "Importantly PLK1 inhibition strongly radio-sensitized medulloblastoma cells." (PMID 27538997, 2016). "We determined whether BI 2536, like PLK1 siRNA, decreases proliferation of medulloblastoma cells." (PMID 22390279, 2012). "Altogether, these findings demonstrated that PLK1 inhibition stabilizes FBXW7 in MYC-driven MB, thus revealing an important function of FBXW7 in suppressing medulloblastoma progression." (PMID 33494392, 2021). "We then evaluated the expression of MYC, PLK1, and FBXW7 in a panel of well-characterized medulloblastoma cell lines." (PMID 33494392, 2021). "Together, these data indicated that FBXW7 physically interacts with PLK1 and c-MYC, and it induces the ubiquitination and proteasome degradation of PLK1 and c-MYC in medulloblastoma." (PMID 33494392, 2021). "Group 3 cell lines expressed lower levels of the FBXW7 protein and higher levels of the PLK1 and MYC proteins compared with the SHH group or normal cerebellum, further confirming the inverse relationship of FBXW7 and MYC/PLK1 in medulloblastoma." (PMID 33494392, 2021). "Such a reciprocal activation is also reported between PLK1 and MYCN, one of the well-known genes highly expressed in SHH medulloblastomas." (PMID 31185958, 2019). "Using the MTS assay, we found a significant decrease in cell proliferation of two different medulloblastoma cell lines, Daoy and ONS-76, transfected with PLK1 siRNA compared to control siRNA." (PMID 22390279, 2012). "In order to test whether a similar mechanism exists in c-MYC-driven medulloblastoma, we examined c-MYC protein levels in MB D458 cells treated with PLK1 inhibitors PCM-075 and BI6727." (PMID 33494392, 2021). "Analysis of gene expression in two independent cohorts revealed that PLK1 mRNA is overexpressed in some, but not all, medulloblastoma patient samples when compared to normal cerebellum." (PMID 22390279, 2012). "Furthermore, targeting PLK1, SETD8, and facilitator of chromatin transcription (FACT) with their respective inhibitors onvasertib, UNC0379, and CBL0137 has also shown preclinical activity against MYC-amplified medulloblastoma." (PMID 37568705, 2023).